TMEM207 (transmembrane protein 207)
Synonyms: UNQ846
Tractability: Antibody: UniProt predicts a signal peptide or a membrane-spanning region.
Gene: Protein-coding gene on chromosome 3 (190,428,655 to 190,449,901, reverse strand). Ensembl gene ENSG00000198398.
Subcellular location: Early endosome membrane
Gene Ontology:
Molecular function: protein binding
Cellular component: early endosome membrane
Genetic constraint (gnomAD): Loss-of-function variants: 10 observed, 14.5 expected, observed/expected ratio (o/e) 0.69, 90% interval 0.43 to 1.17. The upper end of that interval is the gene's LOEUF score, 1.17, which puts it in group 5 of 6, group 1 being the genes least tolerant of losing a copy. Missense variants: 183 observed, 162.3 expected, observed/expected ratio (o/e) 1.13, 90% interval 1 to 1.27. Synonymous variants: 65 observed, 63.17 expected, observed/expected ratio (o/e) 1.03, 90% interval 0.84 to 1.26.
Homologues: Orthologues: chimpanzee TMEM207 (97% identical), macaque TMEM207 (94% identical), dog TMEM207 (72% identical), rabbit TMEM207 (71% identical), pig TMEM207 (69% identical), rat Tmem207 (62% identical), mouse Tmem207 (62% identical).
Diseases named in the same sentence as TMEM207 in open-access papers:
TMEM207 is named in the same sentence as 24 diseases in open-access papers, as found by Europe PMC text mining. Sharing a sentence is not in itself a finding about the gene and the disease. The quoted sentences say what the papers report.
oral squamous cell carcinoma (4 papers, 2018 to 2021). "According to an analysis of our previous studies, TMEM207 expression is related to the mucinous phenotype of colorectal cancer, signet ring cell carcinoma in gastric cancer, and oral squamous cell carcinoma." (PMID 31699801, 2019). "In the present study, we examined whether these two ER stress-related proteins, Clptm1L and TMEM207, could be prognostic markers in oral squamous cell carcinoma (OSCC)." (PMID 35047994, 2021).
colorectal cancer (3 papers, 2017 to 2025). A primary or metastatic malignant neoplasm that affects the colon or rectum. "A review by the same authors consolidated emerging evidence that omentin-1 (intelectin-1) may function as a tumor-suppressive adipokine in colorectal cancer, with its local bioavailability tightly linked to the processing chaperone TMEM207." (PMID 41149627, 2025). "Here, we discuss the recent understanding of the role of adipokines in colorectal carcinogenesis and subsequently describe the potent tumor suppressor roles of intelectin-1 and TMEM207 in colorectal cancer." (PMID 28422056, 2017). "The siRNA-mediated downregulation of TMEM207 resulted in polyubiquitination followed by proteasome degradation of intelectin-1 and decreased intelectin-1 secretion by colorectal cancer cells." (PMID 28422056, 2017). "TMEM207 expression was detected in 38 of 216 colorectal cancer tissue samples and displayed a significant inverse correlation with lymph node metastatic status." (PMID 28422056, 2017). "In colorectal cancer, elevated circulating omentin-1 has shown diagnostic accuracy comparable to conventional tumor markers, while intratumoral ITLN1 expression and its stabilization by TMEM207 may serve as independent prognostic indicators and therapeutic modulators." (PMID 41149627, 2025).
lymph node metastasis (3 papers, 2018 to 2025). "In conclusion, the present study demonstrated that the expression of two ER stress-related proteins, Clptm1L and TMEM207 immunoreactivity was closely related to lymph node metastasis with prognostic value in patients with OSCC." (PMID 35047994, 2021). "Coexpression of Clptm1L and TMEM207 was closely related to lymph node metastasis (P=0.000574)." (PMID 35047994, 2021). "Moreover, TMEM207 expression was significantly correlated with lymph node metastasis and poor prognosis." (PMID 29164763, 2018). "Notably, TMEM207-positive tumors exhibited a significantly lower incidence of lymph-node metastasis (2/38, 5.3%) compared to TMEM207-negative counterparts (54/178, 30.3%; p < 0.001), suggesting a potential role for TMEM207 in limiting metastatic dissemination." (PMID 41149627, 2025). "TMEM207 expression was also related to lymph node metastasis but not to tumour size, age or gender." (PMID 29164763, 2018).
gastric cancer (2 papers, 2018 to 2019). A primary or metastatic malignant neoplasm involving the stomach. "During this gastric cancer cascade, gastric epithelium may gain TMEM207 expression." (PMID 30214895, 2018).
allergic contact dermatitis (1 paper, 2026). An inflammatory skin condition caused by an immune response to direct contact between the skin and an allergen. "In Conclusions, in Allergic contact dermatitis model mice, expression of TMEM207 in the skin decreased regenerative function of the skin, exacerbating the pathological condition of Allergic contact dermatitis." (PMID 41488203, 2026). "Our findings indicate that abnormal expression of TMEM207 is involved in the decline of skin regeneration capacity through YAP, leading to the aggravation of Allergic contact dermatitis." (PMID 41488203, 2026).
colon cancer (1 paper, 2023). "The omentin-1/TMEM207 axis may play a role as a prognostic biomarker of colon cancer in the future." (PMID 37568613, 2023).
cylindroma (1 paper, 2014). "Notably, we also found TMEM207 immunoreactivity in human skin appendage tumors, including cylindroma and spiradenoma (data not shown), as well as in the intradermal tumors of C57BL/6-Tg (ITF-TMEM207) mice." (PMID 25305140, 2014).
leukemia (1 paper, 2019). A malignant (clonal) hematologic disorder, involving hematopoietic stem cells and characterized by the presence of primitive or atypical myeloid or lymphoid cells in the bone marrow and the blood. "TMEM207 (rabbit polyclonal antibody) immunoreactivity was not only observed in granulocytes, monocytes, or leukemia cells infiltrating liver and spleen, but also in megakaryocytes and erythroblasts in bone marrow." (PMID 31699801, 2019).
myeloproliferative disorder (1 paper, 2019). A clonal hematopoietic stem cell disorder, characterized by proliferation in the bone marrow of one or more of the myeloid (i.e., granulocytic, erythroid, megakaryocytic, and mast cell) lineages. "Ectopic TMEM207 expression and Atg4b disruption were associated with the occurrence of myeloproliferative disease-like phenotype in the present transgenic mice." (PMID 31699801, 2019). "Mutations in Atg4b and overexpression of TMEM207 may lead to myeloproliferative disease in the present model." (PMID 31699801, 2019). "TMEM207 expression in bone marrow is likely to be important for myeloproliferative disease occurrence." (PMID 31699801, 2019). "In contrast and more importantly, TMEM207 is expressed in megakaryocytes, erythroblasts and blasts in human myeloproliferative disorders." (PMID 31699801, 2019). "Third, it was observed at high frequency that TMEM207 is expressed in megakaryocytes, erythroblasts and blast cells in human myeloproliferative disorders." (PMID 31699801, 2019). "We concluded that TMEM207 was expressed in hematopoietic cells in human myeloproliferative disease." (PMID 31699801, 2019). "Taken together, the exogenous expression of TMEM207 in bone marrow involving a disrupted Atg4b gene may be responsible for myeloproliferative disease characteristics observed in this study." (PMID 31699801, 2019). "Lastly, TMEM207 could be a molecular target for the development of new therapeutic approaches for patients with myeloproliferative disease." (PMID 31699801, 2019). "Whereas several genetically manipulated animal models of myeloproliferative disease and Atg4b knockout mice exist, this mouse line harboring a genetic mutation in Atg4b and with overexpression of TMEM207 protein did not exist as a model of myeloproliferative disease-like phenotype until now." (PMID 31699801, 2019). "However, although several other genetically manipulated animal models of myeloproliferative disease and Atg4b knockout mice exist, this mouse line harboring a mutated Atg4b gene, and with overexpression of TMEM207 protein, has not been reported as a model of myeloproliferative disease to date." (PMID 31699801, 2019). "However, a mouse model in which Atg4b is disrupted and TMEM207 is overexpressed does not yet exist as a model of the myeloproliferative disease-like phenotype." (PMID 31699801, 2019).
polycystic kidney disease (1 paper, 2022). A usually autosomal dominant and less frequently autosomal recessive genetic disorder characterized by the presence of numerous cysts in the kidneys leading to end-stage renal failure. "Gene-based analysis also highlighted several other genes, including a gene implicated in polycystic kidney disease (TMEM207), a gene expressed at the tight junction of renal tubule epithelial cells (CLDN1), and a gene associated with cell proliferation (GNL2)." (PMID 36275661, 2022).
renal carcinoma (1 paper, 2024). A carcinoma arising from the epithelium of the renal parenchyma or the renal pelvis. "Some proteins of this family are potentially useful for classifying cancer grade in renal cancers (e.g., TMEM45A, TMEM116, TMEM207, TMEM213)." (PMID 38974022, 2024).
cancer (10 papers, 2014 to 2025). A tumor composed of atypical neoplastic, often pleomorphic cells that invade other tissues. "It is believed that TMEM207 ensures omentin is correctly structured and released specifically in the tumor environment, allowing it to act as an anti-cancer agent." (PMID 41149627, 2025). "Overall, addressing the systemic (blood-based) versus local (tumor-based) paradox of omentin requires integrating molecular (TMEM207), environmental (MDSCs/EPCs), and cellular (cancer stem cells) mechanisms." (PMID 41149627, 2025). "Immunohistochemical staining using specific antibodies to Clptm1L or TMEM207 revealed that 31 of 89 tissue specimens exhibited concomitant expression of Clptm1L and TMEM207 at the cancer invasion front." (PMID 35047994, 2021). "Next, TMEM207 expression should be rigorously examined in most cancers or malignant tumors, including rare malignant tumors, i.e., types of sarcoma." (PMID 30214895, 2018). "Recent advances demonstrate that several cancer cell types gain ectopic overexpression of TMEM207 during carcinogenesis, and then abolish the tumor suppressor function of WWOX through competitively binding with its WW domain." (PMID 30214895, 2018). "The signal was localized in the cytoplasm of the cancer cells, as had been the case with anti‐TMEM207." (PMID 29164763, 2018). "Since TMEM207 is also expressed in the cell surface membrane of dysplastic and cancer cells, we are now developing antibody-based approaches targeting several cancers." (PMID 30214895, 2018). "Recent advances highlight that a small transmembrane protein possessing a PPxY motif, called TMEM207, and its relatives are aberrantly expressed in various cancer cells and hinder the tumor suppressor function of WWOX through inhibiting its WW domain." (PMID 30214895, 2018). "In this review, we have summarized the recent findings of pathobiological protein networks that abolish the tumor suppressor function of WWOX in cancer cells, especially focusing on a small transmembrane protein, TMEM207." (PMID 30214895, 2018). "As described in section TMEM207 and Relatives as Undesirable Binding Molecules to WWOX in Cancer Cells, TMEM207 is expressed in intestinal goblet cells for the precise quality control of intelectin-1." (PMID 30214895, 2018). "C57BL/6-Tg (ITF-TMEM207) transgenic mouse lines were generated, in which the TMEM207 gene (which is overexpressed in several human carcinomas) was ectopically expressed under a truncated promoter from the murine intestinal trefoil factor (ITF) gene." (PMID 25305140, 2014). "TMEM207 abolishes the binding of WWOX with HIF-1α to enhance cancer growth." (PMID 32764489, 2020). "In other words, it is presumed that unexpected expression of TMEM207 may take part in promoting cancer growth." (PMID 31699801, 2019). "We propose that this inhibitory mechanism of TMEM207 to WWOX might lead to carcinogenesis if cancer cells continue to express the WWOX protein." (PMID 30214895, 2018). "Overexpression of TMEM207 may participate in cancer metabolism to promote cancer growth." (PMID 30214895, 2018). "As a result, TMEM207 inhibits the various tumor suppressor function of WWOX, leading to the induction of ER stress-related apoptosis in cancer cells." (PMID 35047994, 2021). "We speculate that overexpression of TMEM207 may not be enough to cause gastrointestinal carcinogenesis, but it might promote gastrointestinal cancer progression by enhancing the cancer cell invasion activity, as described in Gastric and Colonic Carcinogenesis section." (PMID 30214895, 2018). "Since the in situ proximity ligation assay is well accepted to detect sub-cellular spatial molecular protein-protein interactions, this finding again verified the interaction of TMEM207 and WWOX in cancer cells." (PMID 30214895, 2018).
cancer (continued). "Combined together with the finding of co-immunoprecipitation assay, which showed the binding of TMEM207 to WWOX as its PPxY motif dependent manner, pathobiological link of TMEM207 and WWOX may be occurred in various cancer cells." (PMID 30214895, 2018). "In addition, we suggest that ectopically expressed TMEM207 may competitively bind to the WW domain of WWOX, thus inhibiting the tumor suppressor function of WWOX during carcinogenesis in certain cancers." (PMID 31699801, 2019). "Notably, we observed TMEM207 immunoreactivity at the cell surface membranes of the dysplastic epithelium neighbouring the OSCC cells, while the signal was cytoplasmic in the carcinoma cells themselves." (PMID 29164763, 2018).
tumor (8 papers, 2014 to 2025). "An interesting finding was that TMEM207 promotes tumor invasion, possibly through binding to a WWOX tumor suppressor molecule and impairing that molecule's tumor suppressive activity." (PMID 31699801, 2019). "Based on the analysis of our previous studies, TMEM207 blocks the tumor suppressor function of WWOX through its PPxY motif." (PMID 31699801, 2019). "A small transmembrane protein, TMEM207, appears to be aberrantly expressed and blocks the tumor suppressor function of WWOX through its PPxY motif." (PMID 30214895, 2018). "As a whole, our findings indicate that the aberrant expression of TMEM207 contributes to tumour progression in OSCC, possibly via promoting aerobic glycolysis." (PMID 29164763, 2018). "Exogenous TMEM207 expression in cutaneous hair follicle bulge cells results in the development of a cutaneous appendage tumour." (PMID 29164763, 2018). "If this is true, circulating omentin might be inactive or simply a marker, while TMEM207-regulated omentin within the tumor microenvironment may exert active anti-tumor effects." (PMID 41149627, 2025). "Developing small molecules or biologics that enhance or stabilize the TMEM207–omentin interaction may promote endogenous production of functional omentin-1, thereby enhancing its anti-metastatic and tumor-suppressive effects." (PMID 41149627, 2025). "We speculate that the aberrant expression of TMEM207 might be an early event during oral carcinogenesis, wherein cytoplasmic TMEM207 binds to WWOX to attenuate the tumour suppressor function of the latter in invasive squamous cells." (PMID 29164763, 2018). "Interestingly, transgenic mice in which murine TMEM207 is overexpressed in cutaneous hair follicle bulge cells spontaneously develop a cutaneous appendage tumor." (PMID 28422056, 2017). "As expected, TMEM207 was expressed in cutaneous adnexal tumor cells." (PMID 25305140, 2014). "Moreover, enforced expression of TMEM207 increased tumour progression in a xenoplant assay." (PMID 29164763, 2018). "Comprehensive cohort studies that concurrently measure circulating omentin-1, tumor-localized ITLN1 expression, its chaperone protein TMEM207, and detailed patient metabolic profiles are thus needed." (PMID 41149627, 2025). "TMEM207 plays a role in the progression of gastric signet‐ring cell carcinoma by binding to WWOX and abrogating its tumour suppressor function." (PMID 29164763, 2018). "TMEM207 competes with WWOX-interacting oncogenic molecules for binding to the WW domain of WWOX, thereby inhibiting the tumor suppressor function of WWOX." (PMID 30214895, 2018). "Enforced expression of TMEM207 abrogated the binding of WWOX to HIF‐1α, increased HIF‐1α and GLUT‐1 expression, even under normoxic conditions, and promoted tumour growth in a xenoplant assay using SAS tongue squamous cancer cells." (PMID 29164763, 2018). "An interesting finding is that TMEM207 facilitates tumor invasion, possibly through binding to WWOX, a tumor suppressor molecule, and attenuating the tumor growth suppression activity of the molecule." (PMID 25305140, 2014). "We propose that highly expressed TMEM207 may competitively bind to the WW domain of WWOX, thus inhibiting the tumor suppressor function of WWOX during carcinogenesis in digestive tract cancers." (PMID 30214895, 2018). "Although further studies are required, TMEM207 and other members of the STMC6 family may constitute a novel transmembrane protein family that hinder the WWOX tumor suppressor function." (PMID 30214895, 2018).
tumor (continued). "Functional knockdown of TMEM207 in CRC cell lines (SW480, RCM-1) led to polyubiquitination and proteasomal degradation of omentin-1, significantly reducing extracellular omentin levels and, by inference, diminishing its tumor-suppressive availability in the microenvironment." (PMID 41149627, 2025).
colorectal (1 paper, 2017). "Moreover, our recent study indicated that loss of TMEM207, which is critical for the proper processing of intelectin-1 in the colon mucosa, leads to insufficient intelectin-1 production, thus participating in colorectal carcinogenesis." (PMID 28422056, 2017).
TMEM207 also shares sentences with these, for which no sentence is quoted: gastrointestinal tumors (2 papers); anemia (1); head and neck cancer (1); lung squamous cell carcinoma (1); neutropenia (1); signet ring cell carcinoma (1); skin appendage tumors (1); spiradenoma (1); Splenomegaly (1); squamous cell carcinoma (1).